FOXP3 (forkhead box P3)
Diseases named in the same sentence as FOXP3 in open-access papers (continued):
Sharing a sentence is not in itself a finding about the gene and the disease.
diabetes (continued). "Furthermore, the frequencies and absolute numbers of FoxP3+ Treg in the SILP were markedly lower in antibiotics-treated animals compared to non-treated mice with MLDS-induced diabetes, as well as the proportion of CD4+ T cells." (PMID 37110604, 2023). "Low-molecular-weight dextran sulfate reduces the incidence of diabetes and even reverses diabetes in early-onset diabetic NOD mice, at least partly via increasing PD-1 expression in T cells, reducing interferon-γCD4 and CD8 T cells, and enhancing the number of FoxP3 cells." (PMID 36704045, 2022). "The development of diabetes caused transcriptional activation of the mammalian target of rapamycin protein kinase gene, as well as increased mRNA expression of the pro-inflammatory cytokines IL1β and IL17A, but did not affect Foxp3 mRNA expression." (PMID 32341701, 2020). "In turn, the level of progression of diabetes is significantly influenced by the Treg subpopulation, the complexity and heterogeneity of which is confirmed by the detection of numerous tissue-specific Tregs, including the so-called VAT Tregs (visceral adipose tissue CD4+Foxp3+ regulatory T cells)." (PMID 32341701, 2020). "Interestingly, co-transfer of Foxp3+BDC2.5+ Treg cells did not prevent diabetes induction in recipient mice as observed for the control group." (PMID 31024566, 2019). "Furthermore, PRL-expanded Treg (CD4+ Foxp3+) population and improved the efficacy of short-term low-dose anti-CD3 treatment (which induce a transient CD4+ and CD8+ T cell depletion) at achieving diabetes remission in the NOD mice." (PMID 29867762, 2018). "TH40 cells isolated from young animals had high FOXP3 levels and could not transfer diabetes; TH40 cells that rapidly and efficiently transferred diabetes were FOXP3 negative regardless of the age of the donor." (PMID 28878738, 2017). "The characteristic features of untreated diabetes progression in NOD mice are the increased infiltration of CD8+ cytotoxic T cells into the islets and pancreatic lymph nodes (PLNs) together with a concomitant decrease in the frequency and activity of CD4+CD25+Foxp3+ Tregs in the same compartments." (PMID 25259810, 2014). "However, adoptive transfer of Foxp3+ BDC12-4.1 cells did not prevent diabetes onset in immunocompetent NOD mice." (PMID 25393309, 2014). "Moreover, Foxp3-deficient mice on the diabetes-prone NOD background develop exocrine pancreatitis and peri-insulitis, but do not manifest invasive insulitis and diabetes." (PMID 23691523, 2013). "To further understand as to whether AG490 prevented and reversed diabetes in treated NOD mice, we measured expression of Foxp3 and other regulatory markers by flow cytometry analysis in different organs of the immune system in NOD mice that were treated with either AG490 or DMSO." (PMID 22615750, 2012). "Therefore, the purpose of the study was to determine the mRNA expression levels of mTOR, Foxp3, IL1β, and IL17A genes in rat parapancreatic adipose tissue with experimental streptozotocin-induced diabetes mellitus, with or without metformin administration." (PMID 32341701, 2020). "Acute ablation of Foxp3+ Treg cells can lead to transiently increased blood glucose concentration in some adult NOD.Foxp3DTR-GFP females, but fails to consistently promote overt diabetes." (PMID 23691523, 2013). "Liposome administration subcutaneously, but not intravenously, induced ChgA-specific Foxp3+ and Foxp3− PD1+ CD73+ ICOS+ IL-10+ peripheral regulatory T cells in prediabetic mice, and liposome administration at the onset of hyperglycemia significantly delayed diabetes progression." (PMID 35336018, 2022).
type 1 diabetes (106 papers, 2006 to 2025). "Consistent with this, the blue module includes known type 1 diabetes–associated genes such as FOXP3 and FOXO3." (PMID 41306972, 2025). "Correcting FOXP3 mutations prevents type 1 diabetes if caught early, and will be a necessary tool in the future of gene therapy and its targets." (PMID 39858654, 2025). "For example, forkhead box P3, or FOXP3, deficiency and mutations can result in immune dysregulation and type 1 diabetes." (PMID 39858654, 2025). "The expression of FOXP3 exon 2 splicing alleles is modulated by glycolysis and controls the Treg induction in multiple sclerosis and type 1 diabetes." (PMID 40007754, 2025). "Mutations in the Foxp3 gene in both mice and humans cause autoimmune and inflammatory diseases such as type 1 diabetes (T1D) and thyroiditis." (PMID 36591309, 2022). "This syndrome of autoimmune driven diarrhea, eczema and often type 1 diabetes, is caused by a multitude of now identified germline mutation in the Foxp3 gene with over 70 mutations." (PMID 34294806, 2021). "Mice and humans with a mutation in the Foxp3 gene display a T cell-dependent, lymphoproliferative immune disorder manifested by some diseases, such as type-1 diabetes, thyroiditis, splenomegaly, and lymphadenopathy." (PMID 32674255, 2020). "Mutations in Foxp3 or Treg deletion in adult mice leads to systemic autoimmune pathology in human and mice, including type 1 diabetes (T1D)." (PMID 31647813, 2019). "Several miRNAs in natural regulatory CD4+ FOXP3+ T cells (nTreg) have been found as markers of disease risk and T cell dysfunction in high-risk type 1 diabetes individuals." (PMID 31708933, 2019). "In this condition, caused by FOXP3 mutations impairing Treg proliferation and function, patients present with a classic triad of enteropathy, eczematous dermatitis, and endocrinopathies, including thyroiditis and type 1 diabetes (T1D)." (PMID 35757131, 2022). "More than 70 mutations in FOXP3 have been described in these patients, and they exhibit a high frequency of polyautoimmunity, such as autoimmune thyroid disease, autoimmune cytopenia, or type 1 diabetes (T1D)." (PMID 35935980, 2022). "In another study, combination therapy with antithymocyte globulin and granulocyte colony stimulating factor increased or preserved beta cell function in individuals with type 1 diabetes when measured 1 year following treatment and this was associated with a higher frequency of FOXP3+ Tregs." (PMID 28770318, 2017). "This decline in Foxp3 expression appears to start as early as 8 weeks of age and becomes more pronounced as the mice become sick, suggesting its association with the development of type 1 diabetes." (PMID 19011680, 2008). "Given the key role that IL-2 signalling plays in maintaining FOXP3 expression, thereby maintaining Treg fitness, it has been postulated that many of the Treg-intrinsic defects observed in type 1 diabetes may be caused by a relative reduction in IL-2 signalling." (PMID 28770318, 2017). "Demethylation progressed gradually, year by year, during 3 years of 11 Foxp3-positive T cell genes, presumably gaining suppressive capabilities against diabetogenic T cells in insulin-dependent diabetes patients." (PMID 40864805, 2025). "In Alvarez, we describe the immunoprotective role of the CD25-biased IL-2 SYNTHORINTM molecule SAR444336 which promotes the generation of functionally-adapted FoxP3+ TREG in a pre-clinical model of type 1 diabetes." (PMID 39704171, 2024). "Treg adoptive transfer therapies have shown promising outcomes, for instance, in patients with type 1 diabetes or in patients with amyotrophic lateral sclerosis, which is a neurological disease wherein FOXP3-expressing cells decrease with disease progression." (PMID 38427731, 2024). "Overall, Tregs in type 1 diabetes cohorts are similar in frequency to control individuals, although a reduction in activated FOXP3+ Tregs in type 1 diabetes has been reported." (PMID 34709423, 2022).
type 1 diabetes (continued). "Reports analysing Tregs concluded that, while the frequency of circulating forkhead box P3 (FOXP3)+CD4+ Tregs is unaltered in type 1 diabetes, their regulatory activity is diminished." (PMID 33084970, 2021). "We recently identified and characterized CD8+ CD25+FOXP3+ Treg cells in the peripheral blood of type 1 diabetes patients." (PMID 31995625, 2020). "Although the proportion of Tregs that express FOXP3 was similar between type 1 diabetes (T1D) and controls, there was a significant change in their Treg signature." (PMID 30740105, 2019). "In mouse models of type I diabetes, as well as in type I diabetic patients, exFoxp3 or Foxp3 expressing cells produce IFNγ 9,11." (PMID 29545616, 2018). "In MS, both an magnification and reduction in FOXP3+ Treg were observed, and in rheumatoid arthritis and newly diagnosed T1D (type 1 diabetes), an increase in FOXP3+ Treg was found." (PMID 30229436, 2018). "Although we found no marked differences in the absolute FoxP3 mRNA levels between GHTg and control mice, immunized GHTg mice had a higher FoxP3/RORγT ratio, concurring to previous results obtained in a model of diabetes type I in NOD-GHTg mice." (PMID 29887869, 2018). "Alterations in the Treg population in type 1 diabetes include increased levels of Treg apoptosis, a decrease in the stability of FOXP3 expression and an increase in the frequency of Tregs that produce proinflammatory cytokines, such as IFN-γ and IL-17." (PMID 28770318, 2017). "Clinical trials have now begun testing therapies that are specifically designed to promote the expansion or function of FOXP3+ Tregs in type 1 diabetes." (PMID 28770318, 2017). "In contrast to studies examining the frequency of Tregs, there is now a large body of evidence to suggest that FOXP3+ Treg function is altered in those with type 1 diabetes." (PMID 28770318, 2017). "Although the defects are not as profound as those seen in individuals affected by IPEX, there is mounting evidence that individuals with polygenic type 1 diabetes display alterations in the fitness and function of FOXP3+ Tregs." (PMID 28770318, 2017). "Nevertheless, we did not observe a difference in IFN-γ production by HELIOS− CD45RA− FOXP3+ Tregs between type 1 diabetes patients and healthy controls (p = 0.79)." (PMID 25652388, 2015). "As it was mentioned, our previous studies showed the association between the −397T>C polymorphism of the estrogen receptor α gene and the quantitative characteristics of regulatory CD4+Foxp3+ T cells in girls with type 1 diabetes." (PMID 24523574, 2014). "It would be in keeping with murine experiments that downregulation of FOXP3 in Tregs results in reduced regulation and worsened disease, as evidenced experimentally in models of type 1 diabetes, where Treg ablation leads to almost immediate onset of disease." (PMID 25092890, 2014). "Frequencies of CD4+Foxp3+ TH17 cells were also enhanced in TT bearing girls with type 1 diabetes and correlated with the level of analyzed cytokines." (PMID 24523574, 2014). "FoxP3 is a potential target for treatment of experimental chronic inflammatory renal disease and type I diabetes." (PMID 16420690, 2006). "In humans, mutations in the FOXP3 gene lead to X-linked autoimmune lymphoproliferative disorder called IPEX (Immune dysregulation Polyendocrinopathy Enteropathy X-linked) syndrome, which includes insulin-dependent diabetes." (PMID 39762647, 2025). "Specifically, MOTS-c promoted the differentiation of CD4+CD25+FOXP3+ regulatory T cells (Tregs), which exhibited low glycolytic activity and showed therapeutic potential in type 1 diabetes (T1D) and other autoimmune diseases, through direct inhibition of mTOR complex 1 (mTORC1) signaling in T cells." (PMID 36670507, 2023).
type 1 diabetes (continued). "The risk of type 1 diabetes (T1D) is higher in patients with IPEX (FOXP3, forkhead box P3), WHIM syndrome, autoimmune polyglandular syndrome type 1 (APS type 1 due to AIRE mutation), CTLA4 mutation, deficiency of LRBA, milder forms of ADA deficiency, and STAT1 GOF." (PMID 37102642, 2023). "The expression of FOXP3 is believed to be modified or reduced in various diseases, including type 1 diabetes (T1D) and multiple sclerosis (MS) in humans, as well as the Scurfy phenotype (which involves the complete absence of T cell regulatory function) in mice." (PMID 37828948, 2023). "This hypothesis might explain why in patients of type 1 diabetes FoxP3+ Treg cells increase at onset of the disease." (PMID 37026009, 2023). "Although these FOXP3 mutations are linked to IPEX, there is an increasing number of patients who do not manifest with the classical triad of early-onset intractable diarrhea, type 1 diabetes (T1D), and eczema." (PMID 38259469, 2023). "This compensatory mechanism may explain why an increase in FoxP3+ Treg cells has been observed in patients with type 1 diabetes at the onset of the disease." (PMID 37026009, 2023). "The studies discussed so far demonstrate reduced FOXP3+ Treg function in type 1 diabetes, but an important caveat is that their conclusions are drawn based on a phenotype found in circulating peripheral Tregs rather than Tregs present at the site of tissue damage." (PMID 28770318, 2017). "However, the use of more accurate markers to define these Tregs, including low expression of CD127 and expression of FOXP3, has led to a consensus that the overall frequency of FOXP3+ Tregs is unaltered in individuals with type 1 diabetes." (PMID 28770318, 2017). "Is reduced FOXP3+ Treg function universal in type 1 diabetes?" (PMID 28770318, 2017). "The analysis of Tregs in peripheral blood of DM1 patients and healthy individuals revealed lower percentage and the absolute number of CD4+Foxp3+ regulatory T cells in diabetic type 1 patients in comparison to healthy individuals from the control group (P = 0.0004 and P = 0.0003, resp)." (PMID 23533301, 2013). "Conventional immunosuppressive functions of CD4+Foxp3+ regulatory T cells (Tregs) in type 1 diabetes (T1D) pathogenesis have been well described, but whether Tregs have additional non-immunological functions supporting tissue homeostasis in pancreatic islets is unknown." (PMID 37577652, 2023). "In support of these concepts, in individuals with type 1 diabetes a wide variety of intrinsic differences within the Treg population has been reported, most of which could be viewed as representing less-fit or less-stable FOXP3+ Tregs." (PMID 28770318, 2017). "Furthermore we have found that the level of Tregs, as well as their ability to express Foxp3, may depend in part on estrogen receptor α polymorphism, which may simultaneously influence the inflammatory response in DM1 (diabetes mellitus type 1) females." (PMID 24523574, 2014). "Type 1 diabetes features a lifelong Treg cell defect; namely, by an increase in resting Tregs (rTregs, or CD4 + CD25 + Foxp3 + CD45RO) and a paucity of activated Tregs (aTregs, or CD4 + CD25 + Foxp3 + CD45RA) compared to nondiabetic controls." (PMID 40869160, 2025). "Impaired glycolysis and reduced Foxp3 exon 2 (Foxp3-E2) expression were also observed in iTregs from patients with relapsing-remitting multiple sclerosis (RRMS) and type 1 diabetes (T1D)." (PMID 41459507, 2025). "In patients with autoimmune diseases, such as type 1 diabetes (T1D) or MS, the frequency of IFN-γ+ Foxp3+ tTreg with lower suppressive activity is augmented in the blood compared to healthy donors." (PMID 36032121, 2022). "Environmental insults in patients with fulminant type 1 diabetes trigger Foxp3 promoter hypermethylation, which then prevents IRF-7 binding to the Foxp3 promoter and impairs Treg development/functionality." (PMID 34622804, 2021).
type 1 diabetes (continued). "DNA vaccination is a promising strategy to induce effector T cells but also regulatory Foxp3+ CD25+ CD4+ Treg cells and inhibit autoimmune disorders such as type 1 diabetes." (PMID 27406624, 2016). "In our previous study, we found that CD4+CD25+High and CD4+ CD25+High FOXP3+ were significantly decreased in total lymphocytes and in CD4+ cells in the recently diagnosed diabetes type I pediatric patients." (PMID 27887663, 2016). "These Foxp3− NR286 T cells functioned as Treg that were able to suppress target T cell proliferation in vitro and inhibit type 1 diabetes in animals." (PMID 19924236, 2009). "Other gene polymorphisms, interleukin-2 receptor alpha (IL2RA), forkhead box P3 (FOXP3), thyroglobulin (TG), CD25, CD40, CLEC16A, and FCRL3, among others, have been found to contribute to both thyroid autoimmunity and type 1 diabetes (Frommer and Kahaly, 2021)." (PMID 41268326, 2025). "The Foxp3 gene was over methylated at baseline in type 1 diabetes and over 3 years became demethylated to a level close to non-diabetic controls." (PMID 34294806, 2021). "Furthermore, in patients with type 1 diabetes, in vitro IL-33 treatment induced regulatory CD4+ CD25high FOXP3+ cell frequencies as well as upregulated the surface expression of ST2 molecule and Foxp3 expression." (PMID 29805313, 2018). "This demonstrates that, if profound, defects in FOXP3+ Tregs can elicit type 1 diabetes in most individuals regardless of other genetic or environmental influences, thus pointing to a key role for these cells in maintaining islet-specific tolerance." (PMID 28770318, 2017). "To date, there are no data on the influence of IL-33 on FOXP3+ regulatory T cells in patients with type 1 diabetes." (PMID 27761063, 2016). "Finally, also markers involved in Treg function such as CTLA-4 and FOXP3 were similarly regulated by 1,25(OH)2D3 or TX527 in T cells from patients with type 1 diabetes after additional proinflammatory cytokine stimulation." (PMID 25279717, 2014). "The therapeutic potential of Foxp3+ Tregs has been demonstrated in various preclinical models such as graft-versus-host disease (GVHD), type 1 diabetes mellitus (T1D), systemic lupus erythematosus, inflammatory bowel disease and multiple sclerosis." (PMID 39676874, 2024). "The dietary indole derivative I3C was found to elevate the CD4+ RORγt+ Foxp3− Th17 cell numbers in the intraepithelial layer, lamina propria, and Peyer’s patches of the small intestine, improving the progression of type 1 diabetes (T1D) in non-obese diabetic (NOD) mice." (PMID 39211042, 2024). "The objective of the study was to identify immune cell populations, in addition to Foxp3+ T-regulatory cells, that participate in the mechanisms of action of tolerogenic dendritic cells shown to prevent and reverse type 1 diabetes in the Non-Obese Diabetic (NOD) mouse strain." (PMID 24465383, 2014). "In non-obese diabetic (NOD) mice (a model of spontaneous type 1 diabetes), Treg cell numbers and Foxp3 expression decrease with the age of the animals, Treg function also declines with aging of the NOD mice, although there were also studies where decrease of Treg frequencies was not discovered." (PMID 25908962, 2014). "However, at least as surprisingly, in several studies FOXP3 and other Treg-expressed molecules, such as TGFB1, have been found to be upregulated in the peripheral blood and intestinal mucosa of patients with CD and related conditions, for example, type 1 diabetes." (PMID 21392369, 2011). "However, in patients with type 1 diabetes mellitus (T1DM, a metabolic disease with local (pancreas) systemic inflammation), circulating CD8+Foxp3+Tregs show a decrease, which further decreases the severity and duration of the disease, independent of the patient’s age." (PMID 41009359, 2025).
type 1 diabetes (continued). "In the non-obese diabetic (NOD) mouse model of type 1 diabetes mellitus (T1DM) development, TCDD activated AHR, increasing Foxp3+ T cells that exert anti-inflammatory effects against effector T cells, preventing T1DM development." (PMID 38612627, 2024). "However, in a murine model of type-1 diabetes, 10-Cl-BBQ almost completely prevented insulitis independent of FoxP3+ Tregs." (PMID 38915403, 2024).